ZNF638 (zinc finger protein 638)
Description:
Transcription factor that binds to cytidine clusters in double-stranded DNA. Plays a key role in the silencing of unintegrated retroviral DNA: some part of the retroviral DNA formed immediately after infection remains unintegrated in the host genome and is transcriptionally repressed. Mediates transcriptional repression of unintegrated viral DNA by specifically binding to the cytidine clusters of retroviral DNA and mediating the recruitment of chromatin silencers, such as the HUSH complex, SETDB1 and the histone deacetylases HDAC1 and HDAC4. Acts as an early regulator of adipogenesis by acting as a transcription cofactor of CEBPs (CEBPA, CEBPD and/or CEBPG), controlling the expression of PPARG and probably of other proadipogenic genes, such as SREBF1 (By similarity). May also regulate alternative splicing of target genes during adipogenesis (By similarity).
Synonyms: NP220; ZFML; MGC26130; Zfp638
Tractability: PROTAC: UniProt records ubiquitination sites on it; ubiquitination databases record sites on it; its protein half-life has been measured.
Gene: Protein-coding gene on chromosome 2 (71,276,537 to 71,437,183, forward strand). Ensembl gene ENSG00000075292.
Subcellular location: Nucleus speckle
Subcellular location (Human Protein Atlas): Nucleoplasm; Vesicles
Pathways (Reactome):
Developmental Biology: Transcriptional regulation of white adipocyte differentiation
Gene Ontology:
Molecular function: RNA binding; double-stranded DNA binding; nucleic acid binding; zinc ion binding
Biological process: RNA splicing
Cellular component: nuclear speck; cytoplasm; nucleoplasm; nucleus
Genetic constraint (gnomAD): Loss-of-function variants: 28 observed, 154.42 expected, observed/expected ratio (o/e) 0.18, 90% interval 0.13 to 0.25. The upper end of that interval is the gene's LOEUF score, 0.25, which puts it in group 1 of 6, group 1 being the genes least tolerant of losing a copy. Missense variants: 2,230 observed, 2,207.9 expected, observed/expected ratio (o/e) 1.01, 90% interval 0.98 to 1.05. Synonymous variants: 779 observed, 748.55 expected, observed/expected ratio (o/e) 1.04, 90% interval 0.98 to 1.1.
Homologues: Orthologues: chimpanzee ZNF638 (99% identical), macaque ZNF638 (96% identical), dog ZNF638 (86% identical), pig ZNF638 (86% identical), mouse Zfp638 (77% identical), rat Zfp638 (77% identical), rabbit ZNF638 (51% identical), tropical clawed frog znf638 (33% identical), zebrafish znf638 (24% identical), zebrafish si:ch211-89o9.4 (6% identical). Paralogues in human: MATR3 (11% identical).
Diseases named in the same sentence as ZNF638 in open-access papers:
ZNF638 is named in the same sentence as 22 diseases in open-access papers, as found by Europe PMC text mining. Sharing a sentence is not in itself a finding about the gene and the disease. The quoted sentences say what the papers report.
hepatocellular carcinoma (2 papers, 2020 to 2025). A malignant tumor that arises from hepatocytes. "To understand the regulatory relationship between USP7 and ZNF638, we inhibited the activity of USP7 in the SK-Hep1 or Huh-7 hepatoma cell line by addition of pharmacological inhibitor P22077 and then observe the protein level of ZNF638." (PMID 33040080, 2020).
brain tumor (1 paper, 2025). "To recapitulate these findings, we demonstrated that ZNF638 exhibited a positive correlation with the HUSH components and a negative correlation with dsRNA-sensing programs in brain tumor tissue based on data derived from the ARCHS4 dataset." (PMID 40091830, 2025).
colon adenocarcinoma (1 paper, 2023). "Most interestingly, we identified two MALAT1-dependent novel molecules, ZNF638 and SENP8, that are associated with significant alterations in colon adenocarcinoma patients’ overall survival and disease-free survival." (PMID 37325561, 2023). "In addition, two of the MALAT1 targets shared across the small intestine and colon, ZNF638 and SENP8, are associated with a change in hazards ratio for overall survival and disease-free survival in human colon adenocarcinoma patients." (PMID 37325561, 2023).
colon adenoma (1 paper, 2023). An adenoma that arises from the colon. "Among the 30 MALAT1-targets shared by both the small intestine and colon, ZNF638 and SENP8 levels are predictive of colon adenoma patient overall survival and disease-free survival." (PMID 37325561, 2023).
colon cancer (1 paper, 2022). "However, in the current state of the research, there are still many ZFPs whose mechanisms of action in colon cancer are not fully understood, and more mechanisms need to be further studied, such as ZNF146, ZNF511, ZNF346, ZNF638, ZNF700, and ZNF768." (PMID 36358661, 2022).
colorectal cancer (1 paper, 2015). A primary or metastatic malignant neoplasm that affects the colon or rectum. "In this study we assess the zinc finger proteins ZNF346, ZNF638, ZNF700 and ZNF768 as capture antigens for the detection of autoantibodies in colorectal cancer." (PMID 25875936, 2015). "In the current study, we validated the presence of autoantibodies to ZNF346, ZNF638, ZNF700 and ZNF768 in colorectal cancer in an independent and larger patient cohort using the well-established ELISA platform." (PMID 25875936, 2015). "Our results indicate that zinc finger proteins ZNF346, ZNF638, ZNF700 and ZNF768 are suitable for use as capture antigens in a blood-based biomarker assay for colorectal cancer." (PMID 25875936, 2015). "We have previously identified autoantibodies to ZNF346, ZNF638, ZNF700 and ZNF768 in colorectal cancer patients using a 37,830-clone recombinant human protein array." (PMID 25875936, 2015).
cutaneous T-cell lymphoma (1 paper, 2015). "In addition, autoantibodies to the zinc finger protein ZNF638 were previously identified in sera of patients with cutaneous T-cell lymphoma using the SEREX (serological identification of recombinantly expressed genes) approach." (PMID 25875936, 2015).
glioblastoma (1 paper, 2025). The most malignant astrocytic tumor (WHO grade IV). "Here, we found that targeting what we believe to be a novel, master epigenetic regulator, Zinc Finger Protein 638 (ZNF638), induces viral mimicry in glioblastoma (GBM) preclinical models and potentiates immune checkpoint inhibition (ICI)." (PMID 40091830, 2025).
glioma (1 paper, 2025). A benign or malignant brain and spinal cord tumor that arises from glial cells (astrocytes, oligodendrocytes, ependymal cells). "Our transcriptomic analysis of 2 independent glioma datasets further confirmed that ZNF638 expression is negatively correlated with expression of components of the dsRNA signaling pathway." (PMID 40091830, 2025). "Our findings suggest that ZNF638 could serve as a target to potentiate immunotherapy in gliomas." (PMID 40091830, 2025). "ZNF638 knockdown induced activity of RIG-I and its downstream effectors in syngeneic murine glioma models, which resulted in increased PD-L1 expression." (PMID 40091830, 2025). "To gain insight into the role of ZNF638 in shaping the epigenetic and immunological characteristics of GBM, we performed immune deconvolution using RNA sequencing from The Cancer Genome Atlas (TCGA) and validated results in an independent institutional cohort of high-grade gliomas." (PMID 40091830, 2025).
liver steatosis (1 paper, 2020). "Although higher expression of both proteins was observed in tumor tissues comparing with para-tumor tissues, the expression of USP7 and ZNF638 was further increased in patients with liver steatosis, and in these patients, USP7 favored nuclear localization." (PMID 33040080, 2020). "To examine the physiological roles of USP7/ZNF638 axis on DNL in vivo, we established the fructose-induced mouse hepatic steatosis model." (PMID 33040080, 2020). "Reasonably, USP7/ZNF638 was also abundantly detected in HCC patients, especially those with liver steatosis, suggesting the central role of USP7 or ZNF638 in DNL-related carcinogenesis." (PMID 33040080, 2020). "The data indicates that USP7/ZNF638 axis mediates aberrant DNL, which is relevant to hepatic steatosis in vivo." (PMID 33040080, 2020). "In the mice liver steatosis model induced by fructose, USP7 or ZNF638 abrogation significantly ameliorated disease progression." (PMID 33040080, 2020). "To fully elucidate clinical relevance of USP7 and ZNF638, we immunostained the HCC specimens with or without liver steatosis." (PMID 33040080, 2020).
melanoma (1 paper, 2025). A malignant, usually aggressive tumor composed of atypical, neoplastic melanocytes. "More importantly, ZNF638 expression was a biomarker of clinical response to immunotherapy across multiple tumor types, including rGBM and melanoma." (PMID 40091830, 2025). "In 3 separate cohorts of patients with melanoma who were treated with anti-PD-L1 or anti-CTLA4 therapy, low ZNF638 was significantly predictive of response." (PMID 40091830, 2025). "Finally, low ZNF638 expression was a biomarker of clinical response to ICI and improved survival in patients with rGBM and patients with melanoma." (PMID 40091830, 2025).
open-angle glaucoma (1 paper, 2022). Chronic outflow obstruction of the eye's drainage canals that can lead to increased internal eye pressure and optic nerve damage. "Moreover, most recently, 127 loci associated with open-angle glaucoma have been identified, with specific genes, such as RERE, VCAM1, ZNF638, SMAD6 potentially conferring open-angle glaucoma risk." (PMID 38983528, 2022).
Sepsis (1 paper, 2020). Sepsis is defined as life-threatening organ dysfunction caused by a dysregulated host response to infection. "The qPCR results were similar to those acquired from microarray, suggest that the 4 lncRNAs (lncRNA lnc-RP11-1220 K2.2.1–7, lncRNA lnc-ANXA3–2, lncRNA lnc-TRAPPC5–1, lncRNA lnc-ZNF638–1) are significantly highly expressed in septic children and could be novel biomarkers for pediatric sepsis." (PMID 32151258, 2020).
steatosis (1 paper, 2020). Increased lipid within the cytoplasm of cells. "Similar results were observed, confirming the higher abundance of USP7 and ZNF638 in steatosis-related HCC." (PMID 33040080, 2020).
tumor (6 papers, 2007 to 2025). "It is unknown how ZNF638 may interact with other markers of response to immunotherapy, such as clonal tumor mutational burden, STING activation, DNA replication stress, and MAPK signaling." (PMID 40091830, 2025). "Furthermore, when stratifying individual tumors based on ZNF638 expression, we identified that low ZNF638-expressing tumors were associated with increased tumor-infiltrating lymphocytes." (PMID 40091830, 2025). "Consistent with increased IP-10 levels, a chemotactic cytokine that attracts T-cells, ZNF638-KD + αPD-L1 tumor had enhanced CD8+ tumor-infiltrating lymphocytes (TILs) compared with other experimental groups." (PMID 40091830, 2025). "Using data from the National Cancer Institute Clinical Proteomic Tumor Analysis Consortium (CPTAC) we further demonstrated that ZNF638, TASOR, MPHOSPH8, SETDB1 proteins were significantly enriched in GBM versus normal brain tissue." (PMID 40091830, 2025). "Here, we have demonstrated that epigenetic activation of retrotransposon transcription through ZNF638 significantly alters tumor immunogenicity and improves survival via induction of viral mimicry." (PMID 40091830, 2025). "ZNF638 knockdown altered the GBM tumor microenvironment by enhancing immunogenicity through elevated Type 1–IFN responses and increased CD8+ T cell infiltration." (PMID 40091830, 2025). "Importantly, our results demonstrated that ICI treatment significantly improved survival and reduced overall tumor growth in syngeneic GBM mouse models with ZNF638 knockdown." (PMID 40091830, 2025). "Overall, ZNF638 is a biomarker of clinical response to ICI in GBM, suggesting that ZNF638 expression could not only predict clinical responses but may also serve as a target to potentiate immunotherapy across multiple tumor types." (PMID 40091830, 2025). "A total of 139 EC tumor tissues were used to show the positive correlation between the expression of RBM25 and PSI value of SEC23A-27345-AP and ZNF638-53926-AP and the negative correlation between RBM25 and PSI value of SEC23A-27346-AP and ZNF638-53927-AP." (PMID 34676158, 2021). "In addition, interference of ZNF638 or USP7 was able to inhibit migration and invasion of fructose-induced tumor cells." (PMID 33040080, 2020).
cancer (3 papers, 2007 to 2023). A tumor composed of atypical neoplastic, often pleomorphic cells that invade other tissues. "Autoantibodies to ZNF638 were detected in sera of 10 out of 96 CRC patients (10.4%) and 1 out of 35 non-cancer control samples (2.9%)." (PMID 25875936, 2015).
ZNF638 also shares sentences with these, for which no sentence is quoted: multiple sclerosis (5 papers); cholangiocarcinoma (1); glaucoma (1); head and neck squamous cell carcinoma (1); infection (1); Parkinson disease (1).